Y_RNA (Y RNA )
Gene: Miscellaneous RNA gene on chromosome 17 (38,089,399 to 38,089,500, forward strand). Ensembl gene ENSG00000275006.
Homologues: Orthologues: chimpanzee Y_RNA (96% identical), macaque Y_RNA (93% identical). Paralogues in human: Y_RNA (100% identical), Y_RNA (98% identical), Y_RNA (87% identical), RNY3 (86% identical), Y_RNA (86% identical), Y_RNA (85% identical), RNY3P1 (84% identical), Y_RNA (84% identical), Y_RNA (83% identical), RNY3P9 (82% identical), Y_RNA (82% identical), RNY3P16 (81% identical), and 95 more.